IL12A (interleukin 12A)
Diseases named in the same sentence as IL12A in open-access papers (continued):
Sharing a sentence is not in itself a finding about the gene and the disease.
cervical cancer (4 papers, 2013 to 2023). A primary or metastatic malignant neoplasm involving the cervix. "The minor allele in IL12A rs568408 has been associated with numerous neoplasms such as hepatocellular carcinoma, cervical cancer, colorectal cancer or osteosarcoma." (PMID 28525983, 2017). "The IL-12A gene was related to enhanced risk of cervical cancer." (PMID 36185274, 2022). "In addition, more meta-analyses have shown that potentially functional polymorphisms of IL12A and IL12B are thought to increase the risk of malignancies such as gastric, lung, and cervical cancers." (PMID 36950684, 2023).
colorectal cancer (4 papers, 2014 to 2022). A primary or metastatic malignant neoplasm that affects the colon or rectum. "The inflammatory cytokines such as IL (interleukin)-6, IL-8, IL-10, IL-12a and NOS2a (nitric oxide synthase), are positively correlated to miR-21 expression in colorectal cancer adjacent tissues, both of which are independent contributors to the poor prognosis of colorectal cancer." (PMID 24936152, 2014). "A strong correlation between the frequency of non-suppressive Foxp3lo T cells and the transcription levels of IL-12A and TGF-β1 in colorectal cancer tissues contributed to a better prognosis in colorectal cancer patients." (PMID 35493450, 2022).
African trypanosomiasis (3 papers, 2014 to 2022). "PBS and CLR test approaches have both indicated PSGs including IL12A, LAMA4, MYD88, SPAST and BOLA to confer resistance mechanisms towards the African trypanosomiasis and tick infestation." (PMID 35428239, 2022). "Regarding the 16 up-regulated genes, S100A3, AXL, IL12A, XPC and FAS identified GO terms such as positive regulation of natural killer cell activation, response to UV-B, African trypanosomiasis, allograft rejection and Type I diabetes mellitus." (PMID 24756038, 2014). "Notable differences were the absence Il12a and Il12b from the rodent brain profiles and the absence of IlIa from African trypanosomiasis ID5143." (PMID 34762691, 2021). "Of the 38 African trypanosomiasis ID5143 pathway genes nine could not be detected including Kng1 and 2 encoding the kallikrein-kinin hormonal cascade in addition to Il12b and the E-selectin gene Sele while the levels Il12a, Apoa1, Fasl and Plcb2 message were subthreshold." (PMID 34762691, 2021).
allergic disease (3 papers, 2006 to 2021). An immune response that occurs following re-exposure to an innocuous antigen, and that requires the presence of existing antibodies against that antigen. "In animal studies, BPS was associated with cytokines related to allergic reactions, such as IL-6, IL12a, and interferon c." (PMID 34822682, 2021). "IL12A has been implicated in T-cell development and may thus influence the development of atopy and allergic diseases." (PMID 18671862, 2008). "Macrophage engulfed microorganism are leading to IL12p70 production, a heterodimer of IL12p40 (IL12B) and IL12p35 (IL12A), which is a primary inducer of Th1 cell development and a critical factor in the development of allergy." (PMID 16600026, 2006).
Alzheimer disease (3 papers, 2017 to 2021). A progressive, neurodegenerative disease characterized by loss of function and death of nerve cells in several areas of the brain leading to loss of cognitive function such as memory and language. "Several polymorphisms have been described in the IL-12A gene and some of them have been associated with susceptibility to Graves' and Alzheimer's disease." (PMID 28321150, 2017).
atherosclerosis (3 papers, 2014 to 2022). A disease characterized by the build-up of fatty material and calcium deposition in the arterial wall resulting in partial or complete occlusion of the arterial lumen. "IL-12A polymorphisms have been associated with the risk of coronary artery disease, and it has been suggested that different components of IL-35 (such as IL-12A) could influence the progression of atherosclerosis." (PMID 36292963, 2022). "In an atherosclerosis model induced by a high-fat diet, Il12a deletion ameliorated atherosclerotic lesion formation and macrophage infiltration in apolipoprotein E (ApoE) KO mice." (PMID 34276358, 2021). "Thus, it could be suggested that TMAO-mediated induction of the miR-17-92 cluster and of SERPINE1 and IL-12A could promote the development of inflammation and atherosclerosis." (PMID 36292963, 2022). "TMAO also increased the expression of two targets of inflammation and atherosclerosis—SERPINE1 and IL-12A—at the gene and protein levels." (PMID 36292963, 2022). "We concluded that TMAO modulates the expression of the miR-17/92 cluster and that such modulation could promote inflammation through IL-12A and blood clotting through SERPINE1 expression, which could ultimately promote atherosclerosis and CVD." (PMID 36292963, 2022).
celiac disease (3 papers, 2009 to 2016). An autoimmune genetic disorder with an unknown pattern of inheritance that primarily affects the digestive tract. "The pathogenesis of celiac disease (CD) has been related to polymorphisms in the regulator of G-protein signaling 1 (RGS1) and interleukin-12 A (IL12A) genes, but the existing findings are inconsistent." (PMID 27043536, 2016). "Hence, the IL12A association and the proximity of IL12RB2 to IL23R (which appears linked to celiac disease), suggest that the genes of the IL12 pathway are particularly interesting to investigate in future genetic studies of celiac disease." (PMID 19175939, 2009).
Graves disease (3 papers, 2017 to 2019). Graves' disease is an autoimmune disorder that leads to overactivity of the thyroid gland (hyperthyroidism).It is caused by an abnormal immune system response that causes the thyroid gland to produce too much thyroid hormones. "IL12A rs568408 seems to be associated with autoimmune disorders: the A allele in IL12A rs568408 was found to be significantly higher in patients with Graves’ disease than in controls." (PMID 28525983, 2017).
melanoma (3 papers, 2022 to 2026). A malignant, usually aggressive tumor composed of atypical, neoplastic melanocytes. "In melanoma, we identified an 8-gene signature (CD28, CD80, CD86, CTLA4, FAS, IFNG, IL10, and IL12A) associated with survival." (PMID 42216340, 2026). "Moreover, the extracts strongly induced the level of released interleukin IL-12A in UVA-irradiated melanoma cells, potentially leading in vivo to the influx of phagocytic cells." (PMID 39682683, 2024). "However, this was expected since only the expression of the IL12A gene encoding the IL-12 p35 subunit was upregulated (Figure A2a,b), and the complete IL-12 p70 protein was not secreted by melanoma cells." (PMID 35563820, 2022).
ovarian carcinoma (3 papers, 2017 to 2024). A malignant neoplasm originating from the surface ovarian epithelium. "Furthermore, FCGBP, MAP4K2, IL12A, and HSPA2 showed similar expression levels in ovarian cancer compared to normal tissues." (PMID 39149564, 2024). "We found no direct link between IL12A/B with ovarian cancer, although pre-activation with IL-12 in ovarian cancer cell lines is shown to improve the efficacy of natural killer cell immunotherapy." (PMID 35406529, 2022).
rheumatoid arthritis (3 papers, 2015 to 2019). A chronic, systemic autoimmune disorder characterized by inflammation in the synovial membranes and articular surfaces. "IL-12A has been linked to celiac disease and multiple sclerosis, whereas STAT-4 is involved in the development of systemic lupus erythematosus (SLE) and rheumatoid arthritis (RA)." (PMID 25803105, 2015).
acute myocardial infarction (2 papers, 2021 to 2022). Necrosis of the myocardium, as a result of interruption of the blood supply to the area. "Evidence suggests that Il12a participates in the regulation of various cardiovascular diseases, including heart failure, hypertension and acute myocardial infarction." (PMID 34276358, 2021). "Kan and his coauthor reported that Il12a knockout (KO) improves left anterior descending coronary artery occlusion-induced acute myocardial infarction by promoting anti-inflammatory functions of monocytes." (PMID 34276358, 2021). "IL-12A has also been found to be upregulated in myocardial infarction." (PMID 36292963, 2022).
anaemia (2 papers, 2010 to 2015). "CYP2C8 rs11572076 was associated with the risk of anemia (HR 3.4 [95% CI 1.7–6.20], p = 00037), as was IL12A rs568408 (HR 1.98 [95% CI 1.39–2.82], p = 0.00014) and HUS1 rs2037483 (HR 0.54 [95% CI 0.39–0.74], p = 0.00016)." (PMID 25741362, 2015). "In addition, children homozygous for another rare allele (T) in IL12A (rs22431348) were associated with reduced risk of severe anaemia (SA) (P = 0.004; risk ratio, 0.69) and of severe anaemia with any parasitaemia (SAP) (P = 0.004; risk ratio, 0.66)." (PMID 20350312, 2010). "Because the single SNP regression analysis demonstrated that multiple sites within IL12A and IL12RB1 genes are significantly associated with protection from severe malaria anaemia, analysis of LD in these two genes was performed respectively." (PMID 20350312, 2010). "Currently, whether the polymorphisms in IL12A and IL12RB1 observed in this study influence the level and expression of IL12, IL12 receptor and IL23 in vitro in relation to severity of malaria anaemia have being examined in Kenyan children." (PMID 20350312, 2010). "This study has shown strong associations between polymorphisms in the genes of IL12A and IL12RB1 and protection from SMA in Kenyan children, suggesting that human genetic variants of IL12 related genes may significantly contribute to the development of anaemia in malaria patients." (PMID 20350312, 2010).
Anxiety (2 papers, 2021). Intense feelings of nervousness, tension, or panic often arise in response to interpersonal stresses. "Interestingly, among the anxiety- and depression-related DEGs, we found the upregulation of Bcl3, C3, Gpat3, and Tnf in the AMY as well as the increased expression of Crhr2, Nant, Sar1a, and Tgif1 and the decreased expression of Ier2, Il12a, Nrep, and Tnfrsf25 in the ACC." (PMID 33898422, 2021).
Arthritis (2 papers, 2018 to 2023). Inflammation of a joint. "IL-12, a heterodimer of p35 subunit (encoded by IL-12A gene) and p40 subunit (encoded by IL-12B gene), plays an important role in antibody-induced joint inflammation." (PMID 30123371, 2018).
atopic dermatitis (2 papers, 2024). "In atopic dermatitis pathogenesis, inflammatory cytokines of the Th2, Th17, Th1, and Th22 subclasses, such as IL-4, IL-13, IL-17A, INF-γ, IL-12A, and IL-22, play important roles." (PMID 38672764, 2024). "In addition, the inflammatory pathogenesis of atopic dermatitis is influenced by Th1 and Th17 cytokines, interferons (IFN)-γ, IL-12A, and IL-17A." (PMID 38541664, 2024).
coronary artery disease (2 papers, 2017 to 2022). "The aim of the present study was to establish if the polymorphisms of IL-12A and EBI3 genes that encode the IL-35 subunits are associated with the development of premature coronary artery disease (CAD) in Mexican individuals." (PMID 28321150, 2017).
dry eye (2 papers, 2023 to 2024). "Increased expression of NF-kB regulated cytokines (il12a, il12b, and ltb) and the chemokine ccl2 that are involved in dry eye pathogenesis was also observed." (PMID 37036417, 2023). "Expression of NF-kB associated or mediated inflammatory factors that have been found to increase or contribute to dry eye pathogenesis, including myd88, cytokines il12a, il12b (a subunit shared by IL-23 and IL-12), ltb and chemokine ccl2, was evaluated by PCR." (PMID 37036417, 2023). "Studies in animal models demonstrated that LPS up-regulates the expression of IL-12a, IL-1β, and IFN-γ in dry eye, as well as increasing the production of chemokines associated with Th1 cells, ultimately leading to Th1-related dry eye development." (PMID 38898418, 2024).
gastric cancer (2 papers, 2020 to 2025). A primary or metastatic malignant neoplasm involving the stomach. "While rhIL-35 did not directly impact the angiogenesis of HUVEC in vitro tube-forming assays, the supernatant from gastric cancer cells overexpressing IL-35, EBI3, and IL-12A notably enhanced HUVEC angiogenesis." (PMID 39974277, 2025).
influenza (2 papers, 2013 to 2018). An acute viral infection of the respiratory tract, occurring in isolated cases, in epidemics, or in pandemics; it is caused by serologically different strains of viruses (influenzaviruses) designated A, B, and C, has a 3-day incubation period, and usually lasts for 3 to 10 days. "Other downregulated genes after 2-days were pik3r5, akt3a, nfkbiab, hras, mapk14a in hepatitis, pik3r5, akt3a, il1b, il12a, raf1b, map2k1 in influenza and pik3r5, akt3a, nfkbiab, il1b, il12a in measles." (PMID 24069208, 2013).
Insulin resistance (2 papers, 2020 to 2022). Increased resistance towards insulin, that is, diminished effectiveness of insulin in reducing blood glucose levels. "• T cell activation. • Induction of inflammatory molecules like IL8, IL12A, CCL5, CCL19, CCR2, and CCR5. • Contribution to increased insulin resistance secondary to TLR2, TLR4, and TLR10 interaction." (PMID 35422689, 2022). "Notably, significant elevations in IL-2 expression in the AT together with that of other inflammatory mediators (IL-8, IL-12A, CCL5, CCL19, CCR2 and CCR5 and TLRs) in obesity suggests that these factors may contribute cooperatively for insulin resistance induction in this population." (PMID 33004937, 2020).
malaria (2 papers, 2010 to 2012). Malaria is a serious and sometimes fatal disease caused by a parasite that commonly infects a certain type of mosquito which feeds on humans. "The results from this study also suggest that the effects of IL12A and IL12RB1 on malaria disease outcomes most likely result from the long evolutionary history of P falciparum parasite within the human population." (PMID 20350312, 2010).
Mouth ulcers (2 papers, 2019 to 2021). "In conclusion, this GWAS of mouth ulcers identified multiple associated loci including a common variant near IL12A with large effects on risk of mouth ulcers." (PMID 30837455, 2019). "The strongest evidence for association with mouth ulcers across all tissues was at IL12A mirroring the single variant results, with an increase in expression predicted to increase the odds of mouth ulcers (Z-test P = 2.23e−103)." (PMID 30837455, 2019). "Mouth ulcers were found to be highly correlated to SNPs in IL-12A in addition to significant relation to other genes including IL-10." (PMID 34539639, 2021). "This study finds 97 variants which alter the odds of developing non-specific mouth ulcers and replicate these in an independent cohort (n = 355,744) (lead variant after meta-analysis: rs76830965, near IL12A, OR 0.72 (95% CI: 0.71, 0.73); P = 4.4e−483)." (PMID 30837455, 2019).
multiple sclerosis (2 papers, 2013 to 2019). A progressive autoimmune disorder affecting the central nervous system resulting in demyelination. "Therefore, rs485789 is a likely causal variant for multiple sclerosis that acts on IL12A via its effect on CA." (PMID 30650056, 2019).
ovarian tumors (2 papers, 2017 to 2023). "For example, we observed that IL12A and IL12RB2 being upregulated in ovarian tumors of current low‐dose aspirin users compared with never users, which are inflammatory genes included in the cytokine‐cytokine receptor interaction pathway but are also known to enhance Th1 immune response." (PMID 37525619, 2023).
schizophrenia (2 papers, 2016 to 2022). A major psychotic disorder characterized by abnormalities in the perception or expression of reality. "STRING analysis highlighted first-order protein interactions among IL12RB1 and IL12B, IL1B, IL6, and IL12A, all of which have previously been associated with schizophrenia." (PMID 27746755, 2016). "Among pro-inflammatory cytokines, the levels of interleukin (IL)-1α, IL-6, IL-11, IL-12A, IL-15, IL-17A, and granulocyte colony-stimulating factor (G-CSF) in tears were elevated in the schizophrenia group (all P < 0.01)." (PMID 35223927, 2022). "Among pro-inflammatory cytokines, the levels of interleukin (IL)-1α, IL-6, IL-11, IL-12A, IL-15, IL-17A, and granulocyte colony-stimulating factor (G-CSF) in tears were significantly higher in patients with schizophrenia than that in normal controls (all P < 0.01)." (PMID 35223927, 2022).
Sepsis (2 papers, 2021 to 2025). Sepsis is defined as life-threatening organ dysfunction caused by a dysregulated host response to infection. "The CLP model was used to further confirm the protective effect of Il12a in sepsis, and the results showed that Il12a deficiency further decreased the survival rate of mice after CLP challenge." (PMID 34276358, 2021). "In the current study, we determined the function of Il12a in sepsis-related cardiac dysfunction and elucidated its underlying mechanisms." (PMID 34276358, 2021). "In the present study, we clearly revealed the function of Il12a in sepsis-related cardiac dysfunction and elucidated its underlying mechanisms." (PMID 34276358, 2021). "In our study, lipopolysaccharide (LPS) and cecal ligation and puncture (CLP) model were used to mimic sepsis, and cardiac Il12a expression was assessed." (PMID 34276358, 2021). "To investigate the function of Il12a in sepsis-related cardiac dysfunction, we measured the expression of Il12a in the hearts of LPS-treated mice." (PMID 34276358, 2021). "Our data provide evidence that Il12a may represent an attractive target for sepsis-induced cardiac dysfunction." (PMID 34276358, 2021). "In addition, Il12a knockout mice were used to detect the role of Il12a in sepsis-related cardiac dysfunction." (PMID 34276358, 2021). "Our data provide evidence that Il12a may be an attractive target for sepsis-induced cardiac dysfunction." (PMID 34276358, 2021). "However, whether Il12a plays a role in sepsis and sepsis-related cardiac dysfunction is unknown." (PMID 34276358, 2021). "However, the effects of Il12a in sepsis-induced cardiac dysfunction remain unknown." (PMID 34276358, 2021).
type 1 diabetes mellitus (2 papers, 2011 to 2014). A chronic condition characterized by minimal or absent production of insulin by the pancreas. "Whereas in our pathway analysis, more genes are identified as part of Type I diabetes mellitus and Allograft rejection pathways (i.e. CD28, HLA-B, HLA-C, HLA-DMB, HLA-DPA1, HLA-DQA2, HLA-DRA, IL12A)." (PMID 22046267, 2011).
acute GVHD (1 paper, 2022). "A predictive model using five of such polymorphisms (CXCL12 rs2839695, IL12A rs7615589, KIR3DL1 rs4554639, TGFB2 rs5781034 for the recipient and CD48 rs2295615 for the donor) together with the development of acute GVHD grade III/IV improved risk stratification of CMV reactivation." (PMID 35525883, 2022).
aging (1 paper, 2019). A developmental process that is a deterioration and loss of function over time. "On another note, our results also indicated the epistatic effects between the IL12RB2 and IL12A genes in modulating cognitive aging by employing the GMDR method." (PMID 31649612, 2019).
autism (1 paper, 2020). Persistent deficits in social interaction and communication and interaction as well as a markedly restricted repertoire of activity and interest as well as repetitive patterns of behavior. "Weight and fat gain were associated with a shared set of genes including Il12a (atypical autism), and Rhou (Ras homology family member U, innate immunity)." (PMID 32636363, 2020).
brain ischemia (1 paper, 2023). Diminished or absent blood supply to the brain caused by obstruction (thrombosis or embolism) of an artery resulting in neurologic damage. "IL12A is suggested to contribute to chemotactic signaling for neutrophils, together with other chemokines, soon after brain ischemia." (PMID 38002055, 2023).
Candida infection (1 paper, 2021). "The pro-inflammatory cytokine, IL-17A, and its regulatory factors of EBI3 and IL-12A (which combine to form the anti-inflammatory cytokine IL-35) are likely to be highly relevant factors in combating Candida infection." (PMID 34209407, 2021).